CIP2A (cellular inhibitor of PP2A)
Diseases named in the same sentence as CIP2A in open-access papers (continued):
Sharing a sentence is not in itself a finding about the gene and the disease.
cancer (continued). "Linked to its function as an inhibitor of PP2A, a master regulator of cellular signaling, CIP2A expression promotes various cancer driver pathways and thus many aspects of aggressive cell growth such as proliferation, apoptosis resistance or senescence evasion." (PMID 25474139, 2015). "Although abundant evidences had shown that CIP2A is overexpressed in many types of cancer, the role of this protein in cancer progression is still unknown." (PMID 26560124, 2015). "Two recent studies provide support for a nuclear role of CIP2A, first demonstrating that cytoplasmic CIP2A can shuttle into the nucleus when nuclear export factor is inhibited and second showing that CIP2A is enriched in the nucleus of human cancer cells during entry into mitosis 7,30." (PMID 25663244, 2015). "It has also been shown that CIP2A can protect cancer cells from therapy-induced apoptosis." (PMID 25663244, 2015). "Therefore, our study addressed a novel role of CIP2A in mediating cancer progression through interacting with the AKT-mTOR signaling pathway." (PMID 25109354, 2014). "More importantly, CIP2A was recently found to be overexpressed at a high frequency in most types of cancer and may serve as a prognostic predictor." (PMID 24884612, 2014). "New tools and technologies for genomic- or systems-level analysis, in addition to the conventional biochemistry and cell biology approaches are starting to reveal how signaling pathways of CIP2A's “oncogenic nexus” contribute to cancer development, cancer evolution, and drug resistance." (PMID 25015035, 2014). "Our studies not only confirmed the regulation under different treatments but also indicated an alternative way by which CIP2A promotes cancer progression, which is demonstrated by the altered cell proliferation by the introduction of mutant AKT (AKT CA and AKT DN)." (PMID 25109354, 2014). "Their study also showed that celastrol potentiates cisplatin's efficacy by suppressing the CIP2A-AKT pathway indicating that CIP2A inhibitors may represent novel therapeutics for this cancer." (PMID 25015035, 2014). "It appears from the results from different laboratories who studied the tumorigenic involvement of CIP2A, PP2A and c-MYC in different organ-type cancers, that CIP2A forms an important component of the “oncogenic nexus” in concert with PP2A and c-MYC in achieving the tumorigenic effect in cells." (PMID 25015035, 2014). "The magnitude of the extent of involvement of CIP2A in the overall process of oncogenesis in different organ type can be envisaged by a recent article from Danish Cancer Society Research Center (Copenhagen, Denmark) who identified the regulatory circuit involving CIP2A and mTORC1 in tumor cells." (PMID 25015035, 2014). "Since AKT is an important regulator in cancer cell proliferation and tumor cell growth, we tested whether CIP2A-mediated cell proliferation can be partly attributed to the AKT phosphorylation." (PMID 25109354, 2014). "This study also demonstrated the clinical relevance regarding targeting of oncogenic CIP2A for future cancer therapies based on the fact that CIP2A expression can be systematically inhibited without severe consequences to normal mouse development and viability." (PMID 25015035, 2014). "Our data suggest a novel “off-target“ mechanism of tamoxifen and suggest that CIP2A/PP2A/p-Akt signaling may be a feasible anti-cancer pathway." (PMID 25228280, 2014). "Although CIP2A has been shown to be overexpressed in a number of solid as well as myeloid cancers, it is evident that there are only a handful of reports regarding the involvement of CIP2A in each of the organ type cancers." (PMID 25015035, 2014). "In addition to its biological significance in the promotion of malignant transformation of human cells, CIP2A also plays important roles in carcinogenesis and the progression of human cancers." (PMID 24884612, 2014). "Additional functions of CIP2A in cancer progression are still under investigation." (PMID 25109354, 2014).
cancer (continued). "Interestingly, CIP2A has recently been identified as an endogenous PP2A inhibitor in human cancer cells using the tandem affinity purification method." (PMID 24884612, 2014). "CIP2A is an oncoprotein that upregulates p-Akt and promotes cancer cell proliferation and survival." (PMID 24335617, 2013). "Whether currently known autophagy inhibitors such as bafilomycin A1, 3-MA or chloraquine can synergize with these CIP2A-inhibiting agents to kill cancer cells warrants future studies." (PMID 23383345, 2013). "Second, our data strengthen the case for the use of CIP2A as an anti-cancer target." (PMID 22537901, 2012). "However, other mechanisms contributing towards increased CIP2A expression in human cancers still remain elusive." (PMID 21445343, 2011). "However, prior to this study, the mechanisms by which CIP2A expression is induced in human cancer cells have been very poorly understood." (PMID 21445343, 2011). "However, treatment of cancer cells with various signaling pathway inhibitors revealed that CIP2A mRNA expression was sensitive to inhibition of EGFR activity as well as inhibition or activation of MEK-ERK pathway." (PMID 21445343, 2011). "In addition to its overexpression in cancers, recent studies have shown that CIP2A immunopositivity correlates with aggressive disease and/or poor patient survival in several cancer types." (PMID 21445343, 2011). "Thus, ETS1 is probably mediating high CIP2A expression in human cancers with increased EGFR-MEK1/2-ERK pathway activity." (PMID 21445343, 2011). "Therefore, elucidation of mechanisms contributing towards CIP2A stability in cancer cells will be a relevant question to be addressed in the future." (PMID 21445343, 2011). "However, results of our siRNA experiments in three different cancer cell lines show positive regulation of CIP2A expression by ETS1." (PMID 21445343, 2011). "Consistent with CIP2A mRNA expression profile, the presence of the CIP2A protein was found in 75 of 107 (70%) of cancer samples, whereas only 6 of 19 (32%) tumour adjacent tissues and 1 of 6 (17%) normal renal tissues exhibited weak or diffuse CIP2A expression (P<0.0001)." (PMID 22075943, 2011). "Therefore, effective therapeutic responses against cancer cells may be most effective with both inhibition of kinase signaling pathways (such as CIP2A and its signaling) and the reactivation of downstream signaling, such as PP2A." (PMID 41155727, 2025). "Therefore, the regulation of PP2A by CIP2A is crucial in cancer initiation and progression." (PMID 41155727, 2025). "Therefore, CIP2A plays important roles in carcinogenesis, and more efforts to dissect its biological functions may help develop CIP2A inhibitors to treat cancers." (PMID 38321019, 2024). "However, we found that CIP2A, a protein that is overexpressed in cancers and shown to bind MYC and prevent PP2A from dephosphorylating Ser 6233, was robustly downregulated upon treatment with either YM155 (compare lanes 1 and 2 for each cell line) or siRNAs that target Survivin." (PMID 36581205, 2022). "As a result, inhibition of CIP2A could be used as a promising therapeutic target in cancer therapy." (PMID 36555359, 2022). "However, when PP2A inhibitor proteins, such as SET and CIP2A, are overexpressed, as is frequently found in human cancers, decreased PP2A activity allows enhanced NELF-A phosphorylation; this causes aberrant upregulation of IEGs and associated downstream growth-promoting genes, and tumor progression." (PMID 36463234, 2022). "Hence, CIP2A is considered as a predictive marker of cancer prognosis." (PMID 33948919, 2021). "The underlying mechanism by which CIP2A regulates PP2A activity and other cellular functions could to be explored in future studies, which will further advance our knowledge in terms of the function of CIP2A and facilitates the finding of new targets for anti-cancer drug development." (PMID 33948919, 2021). "Other study suggested that CIP2A may play a role in anti-cancer growth." (PMID 33948919, 2021).
cancer (continued). "Biological variables associated to a high risk of progression included CIP2A levels, the expression levels of the polycomb group BMI1 gene, the activation of beta-catenin, specific gene signatures, and mutations in cancer-associated genes such as ASXL1, IKZF1, RUNX1, SETD1B, GATA2, MLL, and UBE2A." (PMID 31709190, 2019). "In addition, the inhibition of PP2A which could be inhibited by CIP2A activates PI3K/AKT signaling through regulating the phosphorylation of AKT at Ser473 in SV40ST-induced human cancer cell transformation." (PMID 27144172, 2016). "Therefore inhibition of CIP2A may have clinical relevance in development of future cancer therapies." (PMID 25474139, 2015). "Therefore, more functional roles of CIP2A in cancer progression need to be explored." (PMID 26560124, 2015). "Therefore, our study proposed a novel function of CIP2A in cancer progression." (PMID 26560124, 2015). "Therefore, the finding that CIP2A is an endogenous PP2A inhibitor may greatly expand our understanding of cellular transformation in cancer progression." (PMID 25109354, 2014). "Furthermore, CIP2A also exhibits the ability to transform human immortalized cells; these results expand the general understanding of the mechanisms that are critical for cancer development and progression." (PMID 24884612, 2014). "However, the mechanism of CIP2A in cancer cell proliferation remains poorly understood." (PMID 25109354, 2014). "Interestingly, erlotinib, as well as its derivatives, could also promote cancer cell death by affecting the same signaling pathway (CIP2A/PP2A/p-Akt)." (PMID 25228280, 2014). "Therefore, suppressing the expression of CIP2A may be an indirect way to reverse tumorigenic phenotypes and to treat cancer patients more efficiently." (PMID 25109354, 2014). "Furthermore, sequencing of the active CIP2A promoter region from altogether seven normal and malignant cell types did not reveal any sequence alterations that would increase CIP2A expression specifically in cancer cells." (PMID 21445343, 2011). "Although we have not exclusively ruled out that either promoter methylation or functional SNPs at the CIP2A promoter might contribute to high CIP2A expression in cancer, our data does indicate that these mechanisms most probably are not relevant for regulation of the CIP2A promoter activity." (PMID 21445343, 2011). "In order to identify mechanisms responsible for high basal expression of CIP2A in human cancer cells, we have in this study systematically analyzed contribution of several potential gene regulatory mechanisms that have been earlier shown to affect gene expression in human cancers." (PMID 21445343, 2011). "Cancerous inhibitor of protein phosphatase 2A (CIP2A), a human cancer protein, exerts carcinogenic activity by activating and inhibiting downstream effectors based on protein phosphatase 2A (PP2A)." (PMID 40066330, 2025). "CIP2A also controls phosphorylation and mitosis, which can affect DNA repair mechanisms, especially in BRCA mutant cancer cells, which lead to genomic instability." (PMID 41155727, 2025). "CIP2A is discussed in the section titled “PD-1, PDL-1 Cancer Immunotherapy Pathway” in the Hallmarks of Cancer above, and in the Section 4 below." (PMID 41154660, 2025). "The CAGE analysis after 8 days of PFOA treatment and on day 21 showed increased expression of CIP2A in the PD-1 and PDL-1 cancer immunotherapy pathway." (PMID 41154660, 2025). "Cancerous inhibitor of protein phosphatase 2A (CIP2A) is a newly identified oncoprotein and a promising therapeutic target for cancer." (PMID 41362702, 2025). "It has been shown that CIP2A and PLK1 interact directly to facilitate spindle assembly and modulate cell cycle progression in cancer cells." (PMID 39657788, 2025). "Depletion of CIP2A is observed to inhibit cell proliferation, migration, invasion, and EMT in vitro in multiple different cancer cell lines." (PMID 41155727, 2025).
cancer (continued). "CIP2A stabilizes c‐Myc by inhibiting PP2A activity, thereby activating a series of pathways that promote cancer progression." (PMID 39399646, 2024). "Euxanthone, a naturally occurring organic compound, has an anti-cancer effect that functions by inhibiting EMT and reducing metastatic potential through repression of CIP2A and regulation of PP2A activity." (PMID 38999976, 2024). "In support of the role of CIP2A in the MYC promotion of cancerous transformation, Puustinen and Jӓӓttela reported CIP2A as an oncoprotein that promotes MYC- and MTORC1-mediated cancer transformation by inhibiting the autophagy pathway." (PMID 38994941, 2024). "SET and CIP2A, as previously discussed, are highly expressed and assist in the reduction of PP2A activity in cancer cells." (PMID 38184584, 2024). "FTY720, an activator of PP2A, reduces the level of CIP2A, implying the consideration of PP2A as a target in cancer therapy." (PMID 38999976, 2024). "We also summarize the carcinogenic role of ncORFs such as pTINCR and HOXB-AS3 in regulating hallmarks of cancer, as well as the roles of ncORFs such as HOXB-AS3 and CIP2A-BP in cancer diagnosis and prognosis." (PMID 39123386, 2024). "PP2A activity is further regulated by several endogenous inhibitors (e.g., KIAA1524/CIP2A, SET), the expression of which is often increased in cancer cells, and by cellular activators (e.g., PTPA), the expression of which is often decreased in tumors." (PMID 37170215, 2023). "CIP2A regulates PP2A and subsequently downstream effects on PLK1, E2F1, Akt, DAPK1, and c-MYC in multiple types of cancer." (PMID 37763671, 2023). "This review describes first the mechanisms of cancer progression by the okadaic acid class of compounds and second those by the SET and CIP2A proteins." (PMID 37097392, 2023). "Studies have confirmed that CIP2A is an essential gene in BRCA1 and BRCA2 mutant cells, finding that the CIP2A-TOPBP1 axis can protect chromosome stability, which is a synthetic lethal target for BRCA mutant cancer." (PMID 36911405, 2023). "Since SET and CIP2A are commonly overexpressed in human cancers, we think that cancer preventive agents can act by reducing the overexpression of SET and CIP2A." (PMID 37097392, 2023). "In cancers, different PP2A complexes are regulated by protein interactions with proteins such as CIP2A, PME-1, SET, or ENSA/ARPP1917." (PMID 36854761, 2023). "While there are ongoing efforts in the cancer field to develop direct small molecule inhibitors of PME1 and CIP2A, these strategies are lagging compared to those that target SET." (PMID 35118387, 2022). "We confirmed that enhanced expression of SET or CIP2A is sufficient to promote strong NELF-A phosphorylation and IEG expression in H1299 cancer cells harboring NRASQ61K." (PMID 36463234, 2022). "Recently, reactivation of PP2A activity using small molecules that either antagonise its inhibitors (SET and CIP2A), or directly activate PP2A, has attracted attention as a new strategy for cancer therapy." (PMID 34244560, 2021). "Naturally, blocking CMA led to reduced degradation of CIP2A and increased stability of MYC, acting a as potential preventative strategy in cancer initiation (CIP2A is referred to as a regulatory protein)." (PMID 34445233, 2021). "Cancerous inhibitor of PP2A (CIP2A) was involved in the development and pathogenesis of many cancer types." (PMID 33948919, 2021). "Compared to MSS cancers, MSI cancers had increased expression of CIP2A and decreased expression of PPP2R1A." (PMID 34911954, 2021). "In terms of disrupting CIP2A, the described inhibitors were primarily discovered as a proteasome inhibitor (bortezomib), EGFR kinase inhibitor (erlotinib), or anti-cancer (celastrol), but indirectly or independently reduce CIP2A expression or activity." (PMID 33322239, 2020). "Recent reports have highlighted the role of the PP2A endogenous inhibitors ANP32A, SET, CIP2A, and ARPP19, and their role in cancer progression." (PMID 32110991, 2020).
cancer (continued). "The main mechanism of PP2A inactivation in cancer is via the overexpression of the endogenous PP2A inhibitors SET (Suvar/Enhancer of zeste/Trithorax) and CIP2A (Cancerous Inhibitor of PP2A)." (PMID 31214504, 2019). "The mechanism of cancer progression with SET and CIP2A will probably be supported by studies of the okadaic acid pathway in rodent carcinogenesis, including hyperphosphorylation of proteins and gene expression of inflammatory cytokines." (PMID 30341686, 2018). "Tumor promotion among rodents with the okadaic acid class compounds is revived in human cancer progression by the endogenous protein inhibitors of PP2A, SET and CIP2A." (PMID 30341686, 2018). "CIP2A inhibits the activity of PP2A on MYC and enhance the MYC protein stability in tumor cell, which promotes the consequential proliferation and cancer progression." (PMID 30044786, 2018). "Cancerous inhibitor of protein phosphatase 2A (CIP2A) is an oncogene, and its expression has been correlated with the prognosis of patients with cancer." (PMID 30063110, 2018). "CIP2A is a recently identified oncogene that inhibits protein phosphatase 2A (PP2A) and stabilizes c-Myc in cancer cells." (PMID 30380781, 2018). "Cancerous inhibitor of protein phosphatase 2A (CIP2A), an endogenous protein phosphatase 2A (PP2A) inhibitor, has been identified as an oncoprotein in promoting cancer initiation and progression of several types of cancer." (PMID 29263916, 2017). "Many endogenous inhibitors of PP2A, like CIP2A and SET, are emerging as key players in cancer cell survival and drug resistance." (PMID 28402257, 2017). "Cellular inhibitors of PP2A (the SET oncoprotein and CIP2A, the cancerous inhibitor of PP2A) are increased in human cancers and lead to overexpression of Myc." (PMID 28280720, 2017). "Lapatinib indirectly inhibited CIP2A transcription by disturbing the binding of Elk1 to the CIP2A promoter and restoring PP2A activity, which led to p-Akt downregulation and cancer cell apoptosis." (PMID 26824320, 2016). "PP2A is a tumor suppressor that can be inactivated in cancer cells due to increased accumulation of the SET and CIP2A oncoproteins." (PMID 27705940, 2016). "Cancerous inhibitor of PP2A (CIP2A) promotes MYC phosphorylation and activity during intestinal crypt regeneration in vivo and in various cancers." (PMID 29527532, 2016). "It was proposed that CIP2A protein promotes cell proliferation by regulating MYC-mediated gene expression, and it mediates cancer progression through interacting with the AKT-mTOR signaling pathway." (PMID 26894380, 2016). "HDAC1 inhibition by (S)-2 or specific siRNAs downregulates CIP2A transcription in three different CRC cell lines, thus restoring the oncosuppressor phosphatase PP2A activity that is reduced in most cancers." (PMID 27029072, 2016). "PP2A can be inactivated in cancer cells due to increased accumulation of the endogenous SET and CIP2A oncoproteins, which bind to different subunits of PP2A to inhibit PP2A activity." (PMID 27705940, 2016). "Cancerous inhibitor of protein phosphatase 2A (CIP2A) is an oncogene shown to promote tumorigenesis and progression of several cancer types." (PMID 25663244, 2015). "Taken together, the results suggest that the mechanism of afatinib in sensitive NSCLC cells is by decreasing CIP2A through a reduction in Elk-1 which restores PP2A activity and leads to p-AKT downregulation, thereby inducing cancer-cell apoptosis." (PMID 25537503, 2015). "However, CIP2A may not be used as an individual diagnostic factor or as biomarker for certain types of cancer cancer; instead it can serve as a valuable factor when combining with other clinically established biomarkers for specific cancer detection." (PMID 26560124, 2015). "Similar to CIP2A, SET plays a role in a variety of cancers and was originally discovered as a chimeric protein." (PMID 25642418, 2014).